ZNF800 (zinc finger protein 800)
Description:
DNA-binding transcription repressor that acts as a master repressor of enteroendocrine cell differentiation. Acts upstream of the endocrine gene network and directly represses expression of enteroendocrine transcription factors, such as NEUROG3, INSM1 and SOX4. In the intestine, prevents enterochromaffin cell differentiation by repressing expression of PAX4, a transcription factor that drives differentiation of enterochromaffin cell and restricts differentiation of other intestinal enteroendocrine cell types. Also involved in the differentiation and development of type B pancreatic cells (By similarity).
Tractability: PROTAC: UniProt records ubiquitination sites on it; ubiquitination databases record sites on it; its protein half-life has been measured.
Gene: Protein-coding gene on chromosome 7 (127,346,790 to 127,431,924, reverse strand). Ensembl gene ENSG00000048405.
Subcellular location: Nucleus; Chromosome
Subcellular location (Human Protein Atlas): Nucleoli; Nucleoli rim; Cytosol
Gene Ontology:
Molecular function: DNA-binding transcription repressor activity, RNA polymerase II-specific; DNA-binding transcription factor activity
Biological process: negative regulation of transcription by RNA polymerase II
Cellular component: chromatin; nucleolus; nucleus; chromosome
Genetic constraint (gnomAD): Loss-of-function variants: 11 observed, 50.82 expected, observed/expected ratio (o/e) 0.22, 90% interval 0.14 to 0.36. The upper end of that interval is the gene's LOEUF score, 0.36, which puts it in group 1 of 6, group 1 being the genes least tolerant of losing a copy. Missense variants: 582 observed, 749.09 expected, observed/expected ratio (o/e) 0.78, 90% interval 0.73 to 0.83. Synonymous variants: 246 observed, 256.98 expected, observed/expected ratio (o/e) 0.96, 90% interval 0.86 to 1.06.
Homologues: Orthologues: chimpanzee ZNF800 (100% identical), macaque ZNF800 (99% identical), dog ZNF800 (99% identical), pig ZNF800 (98% identical), rabbit ZNF800 (97% identical), guinea pig ZNF800 (97% identical), rat Zfp800 (95% identical), mouse Zfp800 (94% identical), tropical clawed frog znf800 (58% identical), zebrafish znf800a (47% identical), zebrafish znf800b (32% identical), Drosophila melanogaster CG10979 (20% identical).
Diseases named in the same sentence as ZNF800 in open-access papers:
ZNF800 is named in the same sentence as 13 diseases in open-access papers, as found by Europe PMC text mining. Sharing a sentence is not in itself a finding about the gene and the disease. The quoted sentences say what the papers report.
lung carcinoma (3 papers, 2023 to 2025). "On the other hand, the host transcript ZNF800 of circZNF800 has been linked to regulation of apoptosis, migration and invasion of lung cancer cells, and acts as an adipogenesis master regulator associated with cardio-metabolic traits." (PMID 37950151, 2023). "There are reports that ZNF800 promotes the progression of lung cancer, leading to poor prognosis in cancer patients, which is similar to our research results in LGG." (PMID 40644416, 2025). "Our results are consistent with those of previous studies in which ZNF800 expression increased in lung cancer cell lines, and the upregulation of ZNF800 expression may contribute to poor prognosis in patients with lung cancer." (PMID 40644416, 2025).
glioma (2 papers, 2023 to 2025). A benign or malignant brain and spinal cord tumor that arises from glial cells (astrocytes, oligodendrocytes, ependymal cells). "Previous studies have suggested that with the improvement of the WHO grade, the prognosis of patients with glioma worsens, indicating that high ZNF800 expression may be associated with poor prognosis in LGG." (PMID 40644416, 2025). "In summary, in the malignant progression of LGG ZNF800 can increase the ability of glioma cells to proliferate, migrate, invade, and other malignant biological behaviors, which in turn leads to a poor prognosis of LGG patients." (PMID 40644416, 2025). "Knockdown of ZNF800 significantly inhibited the proliferation, invasion and migration of the two glioma cells." (PMID 40644416, 2025). "Finally, the effect of ZNF800 siRNA on the invasion of human glioma cells SHG44 and SW1088 was demonstrated through Transwell experiments and wound healing experiments." (PMID 40644416, 2025). "Moreover, knocking down ZNF800 can significantly inhibit the proliferation and invasion ability of glioma cells." (PMID 40644416, 2025). "In addition, Transwell experiments revealed that ZNF800 could increase the ability of low-grade glioma cell invasion, and scratch experiments proved that ZNF800 could increase the ability of low-grade glioma cell migration." (PMID 40644416, 2025). "In order to further investigate the role of ZNF800 in LGG, our research group selected glioma cell lines SHG44 and SW1088 for experiments." (PMID 40644416, 2025). "Genes negatively correlated with ZNF800, such as MAPK3, may act as tumor suppressors that promote autophagy in glioma cells." (PMID 40644416, 2025). "Genes positively correlated with ZNF800 play crucial roles in LGG pathology; for example, SP3 can indirectly induce glioma proliferation and metastasis, play a key role in the malignant biological behavior of gliomas, and lead to poor prognosis for patients." (PMID 40644416, 2025). "First, Western Blot confirmed that ZNF800 protein levels were significantly higher in glioma tissues than in non-tumor brain tissues." (PMID 40644416, 2025). "By reviewing previous studies, we found that CASP2, NCAPG2, BAZ1B, and ZNF800, the genes most positively related to NUP205, were reported as carcinogenic genes in cancer, especially CASP2, NCAPG2, and BAZ1B, which were found to be carcinogenic genes in glioma." (PMID 37284202, 2023).
anaplastic astrocytoma (1 paper, 2025). "In addition, ZNF800 expression was the highest in anaplastic astrocytoma (AA)." (PMID 40644416, 2025).
autoimmune disease (1 paper, 2024). A disorder resulting from loss of function or tissue destruction of an organ or multiple organs, arising from humoral or cellular immune responses of the individual to their own tissue constituents. "Pro103Ser in ZNF800 does not associate with other autoimmune diseases or with cancer overall, but is associated with ovarian cancer (OR = 1.29, P = 8.1 × 10−5) and breast cancer (OR = 1.10, P = 3.2 × 10−5) in the same direction as with AITD and the signals co-localize." (PMID 38982041, 2024).
glaucoma (1 paper, 2024). Increased pressure in the eyeball due to obstruction of the outflow of aqueous humor. "In this study, the SNPs with high OR values for cataract exposure on glaucoma were ZNF800 (rs62621812 with OR = 1.213), LOC338694;MYEOV (rs79721202 with OR = 1.144), BMP3 (rs72868578 with OR = 1.131), SOX2-OT (rs9823623 with OR = 1.093), and BET1L (rs11245997 with OR = 1.085)." (PMID 38674349, 2024).
type 2 diabetes (1 paper, 2022). "Moreover, module M7, which is enriched for beta cell markers and type 2 diabetes GWAS candidates, highlights hub genes such as ZNF800, which is closely associated with PAX4, important in the development and differentiation of beta cells." (PMID 34554282, 2022). "Key mediators of the injury responses in islets transgenic for human IAPP or those from individuals with type 2 diabetes include STAT3, NF-κB, ESR1 and CTNNB1 by transcription factor analysis and COL3A1, NID1 and ZNF800 by gene regulatory network analysis." (PMID 34554282, 2022).
cancer (6 papers, 2020 to 2025). A tumor composed of atypical neoplastic, often pleomorphic cells that invade other tissues. "Two representative DIRs are displayed here, which were downregulated (ZDHHC8) and upregulated (ZNF800) in five cancer types, respectively." (PMID 38067392, 2023). "On the other hand, the gene product of the host transcript ZNF800 has only been reported as a candidate master regulator in adipose gene expression and cardio-metabolic traits; ZNF800 involvement in cancers has yet to be demonstrated." (PMID 33114016, 2020). "ZNF800 is a novel gene affecting the malignant progression of several cancers." (PMID 40644416, 2025).
tumor (3 papers, 2010 to 2025). "To verify the correlation between ZNF800 and the immune checkpoint PD-L1, we performed PD-L1-specific immunohistochemical staining analysis on mouse tumor tissue sections." (PMID 40644416, 2025). "Based on the potential value of anti-tumor immunotherapy, we systematically analyzed the relationship between the expression of ZNF800 and immune cell infiltration and multiple well-known immune checkpoints in the LGG immune microenvironment." (PMID 40644416, 2025). "In order to investigate the mechanism of ZNF800’s role in tumorigenesis, this study conducted in vivo animal model experiments and constructed a subcutaneous tumor model." (PMID 40644416, 2025). "Eventually, after the mice were euthanized, the tumor weight was measured, and it was found that there was also a significant decrease in tumor weight in the ZNF800 knockdown group." (PMID 40644416, 2025). "The experimental results showed that 28 days after inoculation, the tumor volume was significantly reduced in the ZNF800 knockdown group compared to the control group." (PMID 40644416, 2025). "Comprehensive immunological analyses showed that highly expressed ZNF800 was positively correlated with the immune checkpoint PD-L1, confirming that ZNF800 may be a potential target for anti-tumor immunotherapy in LGG patients." (PMID 40644416, 2025). "However, the complexity of the tumor immune microenvironment makes it difficult for a single study to fully reveal the regulatory network, and this study only explored the relationship between ZNF800 and immune cell infiltration and immune checkpoint sites in the LGG immune microenvironment." (PMID 40644416, 2025). "However, whether ZNF800 can promote or inhibit tumor growth remains poorly understood." (PMID 40644416, 2025). "From this, therefore, we hypothesized that in the pathological process of LGG, ZNF800 activates the cell cycle by interacting with PAX4, SOX4, and so on, from promoting malignant tumor progression." (PMID 40644416, 2025). "In clinical biopsies, circZNF800 expression, determined by qRT-PCR, was significantly higher in CRC tumor tissues than in the paired adjacent normal tissues analyzed (n = 30), whereas the ZNF800 transcript levels were not significantly altered between the tumor and normal tissues (left two panels)." (PMID 37950151, 2023).
ZNF800 also shares sentences with these, for which no sentence is quoted: astrocytomas (1 paper); breast carcinoma (1); colorectal cancer (1); oligodendroglioma (1); ovarian carcinoma (1).